CPP (ceruloplasmin pseudogene)
Gene: Processed pseudogene on chromosome 8 (91,157,285 to 91,158,748, forward strand). Ensembl gene ENSG00000253525.
Diseases named in the same sentence as CPP in open-access papers:
CPP is named in the same sentence as 6 diseases in open-access papers, as found by Europe PMC text mining. Sharing a sentence is not in itself a finding about the gene and the disease. The quoted sentences say what the papers report.
ependymal neoplasms (1 paper, 2019). "Unlike CPP and ACPP, CPC poses a diagnostic challenge for the pathologist, as tumors need to be differentiated from ependymal neoplasms or metastatic carcinomas." (PMID 31380398, 2019).
CPP also shares sentences with these, for which no sentence is quoted: tumor (2 papers); breast carcinoma (1); cancer (1); enamel caries (1); metastatic carcinoma (1).